TNF (tumor necrosis factor)
Diseases named in the same sentence as TNF in open-access papers (continued):
Sharing a sentence is not in itself a finding about the gene and the disease.
infection (continued). "Consistent with previous reports, TNF-α was not induced upon infection with wild-type M. ulcerans ShT-P strain." (PMID 37910490, 2023). "Notable among these cytokines are TNFα, IL-1β, and IFNγ, where differences in IL-1β and IFNγ secretion between AUD and non-AUD cells were significant and there was a trending higher level of TNFα secretion by AUD cells at 6 and 24 h after infection." (PMID 37786945, 2023). "Infection with A66 resulted in TLR2-dependent TNFα release however, there was no significant impact of TLR4 on TNFα production." (PMID 36897919, 2023). "In contrast, the infected control group had 60.2 ng/mL, 2.3 ng/mL, 1,073.9 ng/mL, and 532.2 ng/mL levels of IL-6, TNF-α, KC, and CRP, respectively, in the 5th h after infection, and these levels decreased by 18.5, 2.3, 10.5, and 8.4 times at the 8th h, respectively." (PMID 37293234, 2023). "Infection of PBECs led to induction of CXCL8, interleukin (IL)-1β, IL-6 and TNF." (PMID 37180449, 2023). "Even against the pathogen infection, the precise mechanism of action of BOT appears to be directed towards the modulation of the epithelial inflammatory response: the reduced expression of TNFα and IL-6 are indicators of a decreased inflammatory tone." (PMID 37841479, 2023). "Thus, we evaluated the expression of two M1 genes (TNFα and CD86) and two M2 genes (IL-10 and CD206) at different time points post-infection under normoxic and hypoxic conditions in human and bovine macrophages." (PMID 36793725, 2023). "Moreover, the expression of immune-related genes (SAA, iNOS, IL-1 β, IL-6, IL-10, TNF α, C3, MHC I, MHC II, CD4, CD8, TCR α, IgM, IgD and IgZ) increased in all groups post infection, which was more significant in the vaccinated groups." (PMID 36969197, 2023). "The treatment with TNF-α without infection (MOCKTNF-α) did not result in the upregulation of IL-6, IL-8, and IP-10 on mRNA level at either 8 h or 24 h." (PMID 37163429, 2023). "At later time points post-infection, the amount of TNFα in the supernatant was higher for infected hypoxic than normoxic human macrophages, confirming that the cytokine levels correlated with the mRNA levels." (PMID 36793725, 2023). "Finally, we detected equivalent levels of IL-2, IFN-y, TNF-α, IL-12, IL-17, IL-22, IL-23, TGF-β, and IL-10 in the lungs of anti-Gr1-treated and control mice during the chronic phase of infection." (PMID 36776848, 2023). "Within the vast array of pro-inflammatory cytokines, TNF-α and IFN-γ, which are the predominant molecules secreted during infection and/or inflammation, may trigger sperm phosphatidylserine translocation or DNA fragmentation." (PMID 36834909, 2023). "The TNF-α levels were reduced in all infection conditions in similar levels without significant changes in comparison with non-infected HUCPVCs." (PMID 37298538, 2023). "Genes such as TNFα, IL10, TLR15, IL8L1 (CXCLi1), IL8L2 (CXCLi2), NOS2, ACOD1 and PTGS2 were upregulated with infection and microbiota, suggesting that macrophages may largely participate in the pro-inflammatory response described in caecal tissues." (PMID 38098020, 2023). "Indeed, GSEAs showed a downregulation of gene sets such as TNF-alpha signalling via NF-κB, IL-6/JAK/STAT3 signalling and inflammatory response after infection with the low-virulence isolate at an early stage of infection." (PMID 37520552, 2023). "For example, ginseng polysaccharide has demonstrated the ability to elevate interleukin-2 (IL-2), interleukin-8 (IL-8), and tumor necrosis factor-alpha (TNF-α) levels, activating Th1 cell-mediated anti-infection immune responses and enhancing immune regulation in the body." (PMID 38035069, 2023). "Altogether, these data indicate that TNF priming licenses BMDMs to engage the caspase-11-mediated non-canonical inflammasome by upregulating inflammasome components in advance of infection." (PMID 37279255, 2023).
infection (continued). "The administration of MSCs to our model of established infection did not reduce the inflammatory cytokines TNF-α, IL-1β, or IFN-γ." (PMID 37175761, 2023). "The absence of cytokines TNF-α and IL-1β resulted in decreased levels of infection, demonstrating that successful infection by T. cruzi requires some activation of NF-kB." (PMID 37242378, 2023). "Th1 cytokines, such as IL-2, IFN-γ, and TNF-α, have been previously reported to be stimulated by GSH in uninfected macrophages and are responsible for the activation and cell recruitment of macrophages to the site of infection." (PMID 37507915, 2023). "Trim32−/− mice had a lower bacterial burden after Lm infection and survived significantly longer than wild-type (WT) mice, as well as lower serum levels of inflammatory cytokines TNF-α, IL-6, IL-18, IL-12p70, IFN-β, and IFN-γ at 1 day post infection (dpi) compared to WT mice." (PMID 37415157, 2023). "Therefore, this study aims to analyze the efficacy of LL-37 cream in enhancing wound healing rate, decreasing the levels of IL-1α, TNF-α, and altering the pattern and number of aerobic bacteria colonization in DFU with mild infection." (PMID 37480520, 2023). "Infection with virulent ASFV isolates often results in exacerbated immune responses, with increased levels of serum pro-inflammatory interleukins (IL-1α, IL-1β, IL-6), TNF and chemokines (CCL2, CCL5, CXCL10)." (PMID 36680273, 2023). "Mouse models of cystic echinococcosis infection showed that the early stage of infection was mainly characterized by increased expression levels of Th1 cytokines, including IFN-γ and TNF-α, which could inhibit or kill the parasite in vivo." (PMID 38187382, 2023). "In conclusion, LL-37 cream enhanced the healing rate of DFU with mild infection, but did not decrease the levels of IL-1α and TNF-α and the number of aerobic bacteria colonization." (PMID 37480520, 2023). "TNF-α levels in the intestine of group D showed an initial increase, then a decrease, suggesting that probably enough TNF-α was released to remove MPs; hence, infection was reduced." (PMID 37998029, 2023). "The infection of bacteria or viruses can trigger type I pro-inflammatory immune responses (e.g., IFN-γ, TNF-α, TH1 cells), whereas infection by helminths typically elicits a type II host resistance and tolerizing immune response (e.g., IL-4, IL-5, IL-13, TH2 cells)." (PMID 37789420, 2023). "The examination of human cytokine levels revealed that while the levels at the primary site of infection were similar for huSGM3 and huNSG mice, strongly increased levels of CCL2, IL-6, IL-8 and TNF-α could be measured by the Luminex assay in the blood." (PMID 36969151, 2023). "TLR genes play an important role in fungi-induced infection resistance because their homologs in the genome are capable of producing proinflammatory factors (type I interferon [IFN], tumor necrosis factor [TNF], and interleukin [IL]) in response to various pathogens." (PMID 37724117, 2023). "Notably, TNF-alpha and IFN-gamma are among the earliest cytokines to be upregulated, often within hours following the onset of cardiac injury or infection." (PMID 38139105, 2023). "In contrast to Th17 cells, IFN-γ+ and TNF-α+ CD4+ Th1 cells were present in roughly similar frequencies in spleen and colon of Irf4+/+ and Irf4-/- mice under steady state conditions as well as following infection." (PMID 37469513, 2023). "We also measured TNF-α and MIP-2 serum levels, which were undetectable on day 10 after infection." (PMID 36808423, 2023). "However, CLEC2.Fc efficiently inhibited the expression of proinflammatory cytokines (IL‐6, TNF‐α, IFN‐γ, and IL‐10) and chemokines (CXCL1, CXCL2, CXCL5, CCL2, IP‐10) at day 3 and day 5 post‐infection (blue columns)." (PMID 37211986, 2023). "Finally, Shi and colleagues reported that treatment with the anti-TNF drug, etanercept, at 2 h p.i. with H1N1 IAV protected mice from otherwise lethal infection." (PMID 36851532, 2023).
infection (continued). "IBD patients on anti-TNF therapy showed significantly higher anti-S-IgG levels after previous SARS-CoV-2 infection (3410 AU/mL (1843–6617 AU/mL)) compared to patients on anti-TNF therapy without previous infection (8434 AU/mL (6227–20,155 AU/mL); p = 0.020)." (PMID 37766088, 2023). "In addition to the robust release of pulmonary IL-6 and G-CSF, similar to infection with chs3Δ, YNB-U-grown cells also induced the expression of additional inflammatory molecules such as IL-1α, TNF-α, and the CCL class of chemokines." (PMID 37538303, 2023). "Lower production of TNF and IFN-γ were observed in this infection model in vivo and in vitro." (PMID 37771590, 2023). "On 3 d post infection, immune response-related pathways were observed, including pathways of Toll-like receptor (TLR), T cell receptor (TCR), chemokine, TNF and NLR, all of which were mainly related to the significant upregulation of Ikbkg protein (NF-κB essential modulator)." (PMID 37587524, 2023). "Infection of keratinocytes leads to an increased production of cytokines interleukin (IL)1ß, IL6, TNFα, IFNß, IFNγ, and chemokines CXCL-1, 2, 8, 10, and CCL20 which are critical for recruiting local immune cells and establishing an antiviral immune state shortly after an infectious mosquito bite." (PMID 37363242, 2023). "Infection of neutrophils and HL-60 cells produce striking quantities of chemokines, including IL-8, RANTES, MIP1α, MIP1β, and MCP1, but not other cytokines observed with in vivo infection, including IFNγ, IL-10, TNFα, IL1β, or IL4." (PMID 37228668, 2023). "TNF-α levels were not different between infection groups and were not different between WT and CF mice within each infection group, with an exception being an increase in WT mice following P. aeruginosa single-species infection (*P<0.05)." (PMID 36748431, 2023). "No significant increase in TNFα levels was seen in the infected neurons, which is of interest because TNFα protects the host cell from infection-induced apoptotic death which is crucial for host cell survival." (PMID 37085774, 2023). "Similar data were reported when comparing anti-TNFs with VEDO or USTE, showing no overall difference in older patients but more infection-related hospitalizations in the anti-TNF-treated patients, with a CCI of >1." (PMID 37443755, 2023). "Here, high levels of cytokines and chemokines (TNF-α, IFN-γ, IP-10, IL-1β, and IL-6), with significantly upregulated TNF-α levels 24 h after infection could be detected." (PMID 37163429, 2023). "In addition, the release of TNF-α and IL-1β induced by BCG (MOI = 10) infection was reversed by siRNA-DUSP1 transfection, indicating that DUSP1 knockdown inhibited the BCG-induced inflammatory response in THP-1 cells." (PMID 36788275, 2023). "Compared with those produced by E. coli DH5α-injected mice, E. coli JE5505-injected mice produced high levels of TNF-α, IL-1β, and RANTES and a low level of IL-10 in their livers, lungs, and sera after infection at indicated time points (3 h or 6 h postinfection; P < 0.05)." (PMID 36916913, 2023). "After 9 h of infection, V. vulnificus-injected skeletal muscle tissues exhibited edema and neutrophil infiltration and exhibited a high transcriptional level of MIP-2, TNF-α, and IL-6." (PMID 36939368, 2023). "The shift from M1 to M2 during the infection course was correlated with the secretion of Th1 cytokines (IFN-γ and TNF-α), changing to Th2 cytokines (IL-10 and IL-13), further indicating that M1 is related to the pro-inflammatory response and M2 to the Th2/regulatory response." (PMID 36668953, 2023). "Consistent with a pro-inflammatory state, LPS-preconditioning significantly increased EPO, IFN-γ, IL-1β, KC, TNF-α, MCP-1, MIP-1α, and IFN-β levels in the lungs and pulmonary FTT infection significantly reduced IFN-γ, IFN-β, and MMP9 levels among LPS preconditioned mice." (PMID 37883420, 2023).
infection (continued). "Levels of proinflammatory chemokines and cytokines CXCL1, CCL5, IFN-γ, IL-1β, CXCL10, IL-17, TNF-α and IL-6 were also assessed in the brain, spleen and liver of MAYV-infected mice throughout the infection." (PMID 36902230, 2023). "MERS-CoV-specific antibodies were reported to persist for at least two years in patients who recovered from the infection, and “memory T cell responses among survivors were polyfunctional, expressing both IFN-γ and TNF, consistent with the greater protective ability”." (PMID 36992136, 2023). "In RNA-seq experiments with a sgRNA targeting DHX38 (seven days post-infection, TNFα treatment), DHX38 was not down-regulated and we found few reads mapping to DHX38 with Cas9-mediated indels (<2%)." (PMID 36928188, 2023). "The top enriched signaling pathway, TNF-α via the NF-κB pathway, showed the largest normalized enrichment score (NES) in untreated versus S. sanguinis multiplicity of infection (MOI) of 20, S. sanguinis MOI of 40, H2O2, and IgG groups (NES = 2.25, 2.53, 2.36, and 2.34, respectively)." (PMID 36645283, 2023). "The expression of the pro‐survival molecules CD127 and Bcl2 was examined in EYFP+ cytokine negative CD4 T cells and those expressing IFN‐γ, IL‐2 or TNF 40 days post‐infection." (PMID 37490492, 2023). "Similarly, infection with DENV-3 P12/08 increased MMP-8 levels, which were suppressed by anti-TNF-α Ab treatment." (PMID 37939119, 2023). "Interestingly, there was a minor upregulation of TNF-α production in response to infection, however, when treated with 30 mM NAC, TNF-α production to infection decreased (p<0.01)." (PMID 37965267, 2023). "IFN-ß and TNF-α treatment before SARS-CoV-2 infection – but not after infection – increased the number of C-to-U substitutions in the vRNA genome in Calu-3 cells." (PMID 36610792, 2023). "When PBC patients were exposed to LPS due to infection, LPS could bind to cell surface receptors (such as TLR 4/CD14) and induced the secretion of pro-inflammatory cytokines (such as TNF-α, IL-1, IL-6, IL-8), promoting inflammation." (PMID 38111586, 2023). "TNF is able to license this pyroptotic death in part by upregulating components of the caspase-11 non-canonical inflammasome ahead of infection." (PMID 37279255, 2023). "The mRNA expression level of TNF-α was not different during infection compared with that in the control group." (PMID 36926518, 2023). "This may be due to the fact that TNF-α and INF-β expression may depend on the activation of other infection pathways on E.coli stimulation in GMECs." (PMID 36604713, 2023). "Similarly, the expression levels of pro-inflammatory response factors (IL-6, TNF-α, CXCL10, CCL7, CXCL11, and CCL2) were significantly decreased at 6 dpi, as compared to virulent WT infection." (PMID 37623322, 2023). "At week 4 post infection, CD4+ T-cells showed a mixed response to S. mansoni AWA by secreting cytokines which encompassed Th1 (IFNγ, TNFα, IL-2 & IL-1β), Th2 (IL-4, IL-5, IL-13) and regulatory responses (IL-10) as well as the regulatory T cell transcription factor Foxp3." (PMID 37837930, 2023). "In addition, some studies found that the levels of IL‐2, IL‐4, IL‐6, IL‐7, IL‐10, IP‐10, MCP‐1, TNF‐α, MIP‐1α, IFN‐γ, and G‐CSF in patients with severe COVID‐19 infection were significantly higher than those in patients with mild and moderate infection." (PMID 36684101, 2023). "The results showed that the protein concentration of inflammatory cytokines in both types of mice was significantly increased after BMA8 strain infection, and the expression of cytokines was higher in BALB/c mice, including IL-2, IL-4, IL-6, IL-10, IL-12p70, KC/GRO, IFN-γ and TNF-α." (PMID 37081549, 2023). "Compared to no infection, MTB infection increased the number of TNF+ lung macrophages and DC at 30 and 60 days after infection." (PMID 37965256, 2023).
infection (continued). "Consistent with the lack of expression of ADAM17 and therefore the inability of D1(A12) to change TNFR2 expression on Merlin-infected cells, blocking of ADAM17 did not significantly alter TNFα-induced cytokine production following infection with Merlin." (PMID 37561786, 2023). "The immune response to Mtb is characterized by a massive influx of immune cells in an attempt to control infection, primarily macrophages and CD4+ T cells, followed by an overwhelming production of cytokines and chemokines, namely tumor necrosis factor (TNF) and interferon-gamma (IFNγ)." (PMID 37274195, 2023). "Therefore, the innate response to in vitro infection of macrophages with both LAMV and WT MeV includes production of IL-6 and TNFα and activation of the NLRP3 inflammasome to release IL-1β and IL-18." (PMID 36851476, 2023). "We also observed significant abrogation of IL-1α and IL-1β release in the absence of gasdermins D and E following infection during TNF priming, indicating that TNF licenses cells to undergo gasdermin-mediated pyroptosis to release IL-1 cytokines." (PMID 37279255, 2023). "Increased serum concentrations of TNF-α and CXCL10 have also been observed after the administration of one vaccine dose after a previous infection, which is of note because the serum CXCL10 concentrations are positively correlated with postvaccine antibody responses." (PMID 36851332, 2023). "Simple stimulation of IMR-90s with TNF-α without infection (MOCKTNF-α) did not result in upregulation of the factors IL-6, IL-8, and IP-10 at mRNA level." (PMID 37163429, 2023). "Recent studies have elucidated the important role of TNF-mediated necroptosis in the inflammatory response, and RIPK1 inhibition has shown therapeutic effects on various rheumatic immune diseases as well as infections." (PMID 37090690, 2023). "Elevated TNF-α levels were noted among individuals with a prior history of infection, although the difference was not statistically significant." (PMID 37833861, 2023). "TNF-α and/or IFN-γ-producing VP6-specific CD4+ T cells were rarely detected in children presenting with or without rotavirus diarrhoea at both acute and convalescent phases of infection, with frequencies mostly below 0.01%." (PMID 37268634, 2023). "CXCL-10, IL-6, G-CSF, MCP-1, TGF-a, TNF-a, MIP-2-A, BAFF, MDC, TRAIL-R2 and MIP-1-A all had at least 2-fold change from mock-infected wells, although many proteins in the panel showed some degree of upregulation post-infection." (PMID 37766362, 2023). "In the present study, expression of inflammatory cytokines (IL-1 β, IL-6, IL-10, TNF α and iNOS) and acute phase protein SAA were up-regulated post infection, especially that of the vaccines immunized groups, indicating that vaccination promoted host innate immunity of M. amblycephala." (PMID 36969197, 2023). "The administration of Xpro-1595, a dominant-negative TNF (DN-TNF) engineered to selectively inactivate soluble TNF (solTNF), has been extensively studied and proven effective in reducing TNF production without suppressing innate immunity during infection." (PMID 38036985, 2023). "Mock-treated TNF−/− mice succumbed to the infection on days 5 or 6 p.i., and there were no beneficial effects of etanercept, oseltamivir, or the combined therapies as all IAV-infected animals succumbed by day 7 p.i." (PMID 36851532, 2023). "Notably, our results showed an upregulated transcriptional expression of cytokines (IL-1β, IL-6 and TNF-α), adhesion molecules (VCAM-1, ICAM-1) and chemokines (CXCL1 and CXCL2) after infection in both brain cortex and hippocampus." (PMID 36778380, 2023). "However, even given this limitation, clear trends were observed, with increases in the pro-inflammatory cytokines TNFα and IL-1β, the regulatory cytokine IL-1RA and the chemokines CCL2, CCL17 and CCL3 in the sputum post-infection." (PMID 37012228, 2023).